TNF (tumor necrosis factor)
Diseases named in the same sentence as TNF in open-access papers (continued):
Sharing a sentence is not in itself a finding about the gene and the disease.
skin toxicities (2 papers, 2022 to 2025). "Acute radiation-induced skin toxicity is associated with elevated levels of various cytokines and chemokines, particularly interleukin-1α (IL-1α), IL-1β, tumor necrosis factor-α (TNF-α), IL-6, IL-8, CCL4, CXCL10, and CCL2." (PMID 41356595, 2025). "In individuals with EGFRI-induced skin toxicities, the levels of various inflammatory cytokines are increased, including IL6, TNFα, and CCL2." (PMID 35324426, 2022).
small intestinal tumors (2 papers, 2015 to 2025). "Liu et al16 found the quantity of inflammatory mediators (IL-6, IL-1β, and TNF-α) in the small intestinal tumors of Apcmin/+ mice was higher than that in the control group." (PMID 40241344, 2025). "The variation in the number of small intestinal tumors could not be explained by the TNFα levels, whereas 31% of the variation in the diameter of small intestinal tumors could be explained by the TNFα levels (P = 0.003)." (PMID 26347815, 2015). "The association found by simple linear regression with diameter of small intestinal tumors and TNFα, body weight evaluated as AUC from week 3 to 11 and nonfasted blood glucose levels at week 6 and week 11, was 31%, 14%, 9% and 8%, respectively (P < 0.001, except for TNFα with P = 0.003)." (PMID 26347815, 2015). "However, feed intake, number and size (data not shown) of small intestinal tumors, GTT results, nonfasted blood glucose levels (data not shown), insulin and TNFα levels were not significantly different between the ob/wt and wt/wt mice." (PMID 26347815, 2015).
spinocerebellar ataxia type 1 (2 papers, 2024 to 2025). Spinocerebellar ataxia type 1 (SCA1) is a subtype of type I autosomal dominant cerebellar ataxia (ADCA type I) characterized by dysarthria, writing difficulties, limb ataxia, and commonly nystagmus and saccadic abnormalities. "In a study of a mouse model of spinocerebellar ataxia type 1 (SCA1), depletion of microglia from the cerebellum during an early stage of the disease using an inhibitor of CSF-R1 resulted in reduced expression of TNF-α, an effect that was associated with improved motor function." (PMID 37950146, 2024). "In Spinocerebellar Ataxia Type 1 (SCA1), NF-κB inhibition in Purkinje cells exacerbated motor deficits by interfering with microglial proliferation and TNF-α production, emphasizing the nuanced role of TNF-α signaling in neuronal circuitry formation." (PMID 41292555, 2025).
spirochetal infections (2 papers, 2011 to 2021). "Through their ability to induce the production of tumor necrosis factor (TNF) by macrophages, spirochete lipoproteins play an important role in systemic and local inflammatory changes that characterize spirochetal infections." (PMID 21816039, 2011).
squamous cell skin cancer (2 papers, 2016 to 2023). "However, many register-based cohort studies and systematic reviews of randomized trials had not identified such an increased risk of overall cancer with the use of anti-TNFα, with the exception of an increased risk of squamous cell skin cancer risk in patients treated with abatacept." (PMID 37554981, 2023).
stress-related disorder (2 papers, 2019 to 2022). Stress-related disorders are mental health disorders that are a result of an atypical response to both short and long-term anxiety due to physical, mental, or emotional stress. "It is reported that increased releases of proinflammatory cytokines such as TNF-α and IL-1β commonly appeared in individuals with stress-related disorders, and the present results revealed that SHXXD could suppress the overexpressed proinflammatory cytokines of TNF-α and IL-1β." (PMID 31178969, 2019).
subacute sclerosing panencephalitis (2 papers, 2023 to 2024). A chronic progressive encephalitis that develops a few years after measles infection and presents with a demyelination of the cerebral cortex. "Positive correlations were found between S100B and TNF-α, S100B and IL-1β, and NF-H and soluble TNF receptor 1 in subacute sclerosing panencephalitis." (PMID 39272777, 2024).
subacute thyroiditis (2 papers, 2023). Self-limited inflammation of the thyroid gland characterized by the presence of multinucleated giant cells. "The study has shown that quercetin, luteolin, kaempferol, and PV beta-sitosterol may play key roles in the treatment of subacute thyroiditis associated with the regulation of inflammation and apoptosis by influencing PI3K-Akt and TNF signaling pathways." (PMID 37631021, 2023). "He relapsed twice after reinitiation of the drug Another case (published in 2021) introduced a 71-year-old male patient with PsA who was treated with secukinumab (IL-17A inhibitor), which was later switched to adalimumab (TNF-α inhibitor), while developing subacute thyroiditis." (PMID 36902323, 2023).
sudden sensorineural hearing loss (2 papers, 2022 to 2023). Sensorineural hearing loss which develops suddenly over a period of hours or a few days. "Although the precise molecular mechanism remains to be elucidated, studies suggest that the serum level of TNF-α may play a key role in the pathophysiology of sudden sensorineural hearing loss." (PMID 37733709, 2023). "Moreover, in vivo loss-of-function analysis demonstrated that TNF-α was a factor that worsened cochlear inflammation and clinical research suggested that there was an increased TNF-α level in sudden sensorineural hearing loss." (PMID 36158549, 2022). "Changes in the serum levels of cytokines, such as tumor necrosis factor-α (TNF-α) and interleukin-6 (IL-6), have been related with poor prognosis in patients with sudden sensorineural hearing loss." (PMID 37733709, 2023). "Reports show that posttreatment serum TNF-α levels are higher than pretreatment levels in patients non-responsive to the treatment of sudden sensorineural hearing loss." (PMID 37733709, 2023).
temporomandibular joint disorder (2 papers, 2017 to 2025). Any condition affecting the anatomic and functional characteristics of the temporomandibular joint. "The COMT, HTR2A, MMPs, IL-1β, IL-6, TNF-α and ESR1 are known to influence the pain perception, inflammation, and joint integrity in temporomandibular joint disorders." (PMID 40291793, 2025).
teratocarcinoma (2 papers, 2021 to 2024). A germ cell tumor characterized by the presence of an embryonal carcinoma component and a teratoma component. "Targeting TNF to EDB delayed tumor growth in teratocarcinoma models compared to untargeted cytokine, and the anti-cancer effect was amplified when co-administered with melphalan or an EDB-specific IL-12 immunocytokine." (PMID 33803078, 2021).
teratoma (2 papers, 2014 to 2023). A non-seminomatous germ cell tumor characterized by the presence of various tissues which correspond to the different germinal layers (endoderm, mesoderm, and ectoderm). "ESC-educated macrophages produce high levels of arginase-1, Tie-2, and TNF-α, which participate in angiogenesis and contribute to teratoma progression." (PMID 25071759, 2014). "We demonstrated that these ESC-educated macrophages (SEM) exhibit an elongated morphology and produce high level of TNF-α, which participates in angiogenesis and contributes to teratoma progression." (PMID 25071759, 2014). "Thus targeting TNF-α by administration of TNF-α antagonists may be a promising option to suppress teratoma angiogenesis." (PMID 25071759, 2014). "Within the ESC implantation site, the presence of Tie-2+ macrophages and TNF-α secreted by ESC-macrophages stimulates angiogenesis and supports teratoma growth." (PMID 25071759, 2014).
teratospermia (2 papers, 2017 to 2023). "Finally, GO Biological Process Enrichment and KEGG analyses identified deregulated signaling pathways in teratozoospermia, including TNF, FoxO, MAPK, and PI3K-Akt pathways." (PMID 37834450, 2023).
testicular germ cell tumor (2 papers, 2024 to 2025). A germ cell tumor arising from the testis. "Lastly, an analysis of patient survival with testicular germ cell tumors along with other types of cancers revealed high expression levels of both TAF7 and TNF, which were strongly associated with poor survival outcomes in patients." (PMID 39457533, 2024). "Interestingly, testicular germ cell tumor patients co-expressing TNF and TAF7 had poorer survival outcomes compared to those with expression of TNF alone." (PMID 39457533, 2024). "Indeed, a low and high expression of TAF7 and TNF in testicular germ cell tumors together could drive poor survival outcomes in patients, while a low and high expression of TAF7 or TNF in tumors alone is associated with extended longevity." (PMID 39457533, 2024). "In testicular germ cell tumor models, TG7 silencing led to reduced viability and upregulation of IL6 and TNFα, suggesting that TG7 might suppress apoptotic or inflammatory signals under physiological conditions." (PMID 41425727, 2025).
testicular tumors (2 papers, 2017 to 2019). "Bialas and colleagues in 2009 investigated the role of IL-6, IL-10, TNF-α-, TNFR1, and TNFR2 in the processes of normal and abnormal spermatogenesis as well as testicular tumors using Real-Time PCR technique." (PMID 29082371, 2017). "Interestingly, in the case of TNF-α and IFN-γ, there was a decrease in the intra-testicular tumour expression of both cytokines." (PMID 31731436, 2019).
thymus (2 papers, 2012 to 2024). "The other theories of thymus atrophy indicate the involvement of other factors, such as the synthesis of IL-6 and TNF-α and leptin deficiency." (PMID 39599720, 2024). "By contrast, mice deficient for IKK2, in which NFκB signaling is impaired, displayed thymus atrophy and an increase in thymocyte cell death induced by TNFα." (PMID 23071785, 2012).
thyroid tumor (2 papers, 2020 to 2025). A benign or malignant neoplasm affecting the thyroid gland. "TNF-α stimulation was reported to increase CCR6+ cells in thyroid tumor lines TPC-1 and BCPAP." (PMID 40150133, 2025).
tick-borne encephalitis (2 papers, 2019 to 2023). Tick-borne encephalitis is caused by an arbovirus of the Flaviviridae family (tick-borne encephalitis virus, TBEV), transmitted principally by the bite of the Ixodes ricinus tick. "The increased serum levels of TNF-α were found in patients of tick-borne encephalitis." (PMID 37378295, 2023).
tooth agenesis (2 papers, 2013 to 2024). A tooth disease characterized by failure to develop one or more missing teeth. "Regarding EDA variant distribution in the four domains, most (44.2%) variants associated with deciduous tooth agenesis were in the TNF homologous domain, consistent with previous findings on EDA variant distribution associated with permanent tooth agenesis." (PMID 39408781, 2024). "EDA is an important gene associated with tooth agenesis, it is located on chromosome Xq12–q13.1 and encodes for ectodysplasin-A (EDA) (MIM 300451), a member of the tumor necrosis factor (TNF) family." (PMID 24312213, 2013).
tracheobronchitis (2 papers, 2015 to 2022). Inflammation of the tracheobronchial tree. "In addition, organic acid component, as the main active ingredient of pugongying, can improve acute tracheobronchitis by downregulating the protein expression levels of TNF-α and IL-6." (PMID 36278166, 2022).
transient arthritis (2 papers, 2023 to 2025). Arthritis that is not permanent. "Among these patients, four had transient arthritis that resolved spontaneously or after treatment with low-dose glucocorticosteroids and two required therapy with a tumor necrosis factor-alpha (TNFα) inhibitor." (PMID 40006724, 2025). "Among the six monocyte-related cytokines/chemokines which peaked at day 1 post-immunization, five (MCP-1, IL-1Ra, TNF-α, IL-10 and IL-6) defined a signature that was vaccine dose-dependent and correlated with viremia, biological outcomes and adverse events, including transient arthritis." (PMID 38235127, 2023).
Tricuspid regurgitation (2 papers, 2009 to 2020). Failure of the tricuspid valve to close sufficiently upon contraction of the right ventricle, causing blood to regurgitate (flow backward) into the right atrium. "Interleukin 6, interleukin 8, interferon-γ, tumor necrosis factor-α, RANTES and PDGF-BB correlated positively with tricuspid regurgitation velocity." (PMID 19956689, 2009).
tubular adenoma (2 papers, 2014 to 2016). A usually polypoid neoplasm arising from the glandular epithelium. "These factors as well as TNF-α were also positively associated with the presence of a tubular adenoma." (PMID 24465801, 2014). "A positive association was also found between TNF-α and risk of tubular adenomas." (PMID 27608842, 2016). "Serum leptin, IP-10 and TNF-α were significantly associated with tubular adenoma presence." (PMID 24465801, 2014). "Participants with the highest concentrations of serum TNF-α were 4.9 (CI: 1.6–14.8) times more likely to have a tubular adenoma than those with serum TNF-α levels in the lowest tertile (p = 0.0054)." (PMID 24465801, 2014). "For each increase in TNF-α tertile, a participant was 2.4 (CI: 1.4–4.0) times more likely to have a tubular adenoma (p = 0.0055)." (PMID 24465801, 2014).
Turner syndrome (2 papers, 2010 to 2019). Turner syndrome is a chromosomal disorder associated with the complete or partial absence of an X chromosome. "After PWM, females produced a lower median level of TNFα than Turner syndrome patients (p < 0.001), while median level in the male group was intermediate, and was not statistically distinct from either of the other groups." (PMID 20525175, 2010). "To investigate gender dimorphism at a cellular level, we evaluated the production of cytokines implicated in inflammatory processes (IL -1, IL- 6, PGE-2 and TNF alpha), in healthy prepubescent children of both sex and Turner's syndrome (TS) patients (genotype XO)." (PMID 20525175, 2010). "The CD8+TNF-α+ cells were higher in Turner's syndrome, as well as the CD14+TNF-α+ monocytes." (PMID 30941138, 2019).
tylosis (2 papers, 2015 to 2017). "It is likely that enhanced EGFR activity and TNFα shedding observed in tissue from patients with tylosis with oesophageal cancer facilitates tumourigenesis through aberrant and exaggerated wound healing, in response to stress within the oesophagus." (PMID 26419362, 2015). "As a consequence of increased ADAM17 activity, tylosis-derived keratinocytes show several features of “constitutive wound healing” in vitro, including rapid closure in scratch-wound assay, and upregulated shedding of ADAM17-dependent substrates such as EGFR-family ligands and TNFα." (PMID 26419362, 2015).
uterine sarcoma (2 papers, 2014 to 2018). "During further experiments exploring the molecular mechanisms of SAHA-induced apoptosis or autophagy, we noticed a remarkable enhanced cytotoxic effect on both uterine sarcoma cell lines when TNF-α was included in our experiments." (PMID 24618889, 2014). "As TRAIL acts in a similar way as TNF-α by binding to the cell membrane receptors DR4/TRAIL-R1 and/or DR5/TRAIL-R2 and by transmitting an apoptotic signal via their cytoplasmic death domain, we investigated whether a SAHA/TRAIL combination treatment enhances cell death in uterine sarcoma cell lines." (PMID 24618889, 2014).
vascular insufficiency (2 papers, 2017). "TNF-α-induced vascular permeability is a critical contributor to the pathophysiology of vascular insufficiency." (PMID 28855900, 2017).
ventricular fibrillation (2 papers, 2011 to 2025). A disorder characterized by an electrocardiographic finding of a rapid grossly irregular ventricular rhythm with marked variability in QRS cycle length, morphology, and amplitude. "Inflammatory cytokines (such as TNF-α, IL-6, IL-1β, IL-17) are involved in the pathogenesis of malignant VAs (ventricular tachycardia (VT) and ventricular fibrillation (VF)), but are largely overlooked in the management of heart rhythm disorders." (PMID 41574188, 2025).
X-linked agammaglobulinemia (2 papers, 2012 to 2026). X-linked agammaglobulinemia (XLA) is a clinically variable form of isolated agammaglobulinemia, an inherited immunodeficiency disorder (see this term), and is characterized in affected males by recurrent bacterial infections during infancy. "Impaired TLR-8-mediated IL-6 and TNF-α production in antigen-presenting cells from patients with X-linked agammaglobulinemia was observed." (PMID 22547990, 2012). "Moreover, the fact that neutrophils isolated from a patient with X-Linked Agammaglobulinemia (Bruton disease) were severely compromised in their ability to produce TNF-α upon stimulation by HS plus LPS further suggested a role for BTK in the stimulation of TNF-α production." (PMID 41596726, 2026).
xanthoma (2 papers, 2014 to 2022). A non-neoplastic disorder characterized by a localized collection of histiocytes containing lipid. "Indeed, an increased concentration of tryptase, TNF-α, IL-8 and IL-6 in plasma from FH subjects with xanthoma as compared to subjects without xanthoma has been previously reported." (PMID 35897824, 2022).
absence seizures (1 paper, 2025). "IL-1β, together with tumor necrosis factor-alpha (TNF-α), was also shown to be upregulated before the onset of seizures in another polygenetic rat model of absence seizures, namely the Wistar Albino Glaxo rats from Rijswijk (WAG/Rij)." (PMID 39851521, 2025).
acneiform rash (1 paper, 2022). "The mHLJD decoction extract reduced the TNFα-induced expression of IL-8, which may exert positive effects on EGFRI-induced acneiform rash." (PMID 36204127, 2022).
Acute bronchitis (1 paper, 2024). Inflammation of the large airways of the lung with rapid onset and short course usually associated with cough, mucus production, shortness of breath, wheezing, and chest tightness. "As summarized in chapter 4.2.1, in vitro and in vivo data indicated that various cytokines and inflammatory mediators were inhibited by DCQAs including IL-6 and TNFα, which seem to play a role during acute bronchitis." (PMID 39239645, 2024).
acute disseminated encephalomyelitis (1 paper, 2020). Acute disseminated encephalomyelitis (ADEM) is a demyelinating disorder of the central nervous system. "Experiment has shown that CoVs play a destructive role in acute disseminated encephalomyelitis (ADEM) correlated with increased inflammatory mediators such as IL-6, IFN-γ, TNF-α, CXCL9, and CXCL10." (PMID 33708124, 2020).
acute endometritis (1 paper, 2023). An acute, usually bacterial infection affecting the endometrium. "In a mouse model of acute endometritis, DNase I has been shown to inhibit the formation of NETs and reduce TNF-α levels through the NF-κB signaling pathway." (PMID 37906560, 2023).
adrenal cancer (1 paper, 2022). A carcinoma involving a adrenal gland. "TNF-alpha can also be a contributing factor to adrenal cancer development and its drug resistance." (PMID 36614027, 2022).
agoraphobia (1 paper, 2015). An anxiety disorder characterized by an intense, irrational fear of venturing out into open places or situations in which help (or escape) might not be available should excessive anxiety or panic symptoms develop. "Associations between lifetime agoraphobia status at baseline and inflammatory measures (tumor necrosis factor-α) at follow-up, serially adjusted for covariates." (PMID 25875094, 2015). "The composite score of proinflammatory markers (including CRP, IL-6 and TNF-α) at follow-up was higher (model 5: β = 0.578 (95%-CI 0.241–0.915) among subjects suffering from lifetime agoraphobia at baseline." (PMID 25875094, 2015). "In addition, the effect size of agoraphobia for TNF- α was higher than those of all the other covariates, except for drug dependence." (PMID 25875094, 2015).